DEPDC1 (DEP domain containing 1)
Diseases named in the same sentence as DEPDC1 in open-access papers (continued):
Sharing a sentence is not in itself a finding about the gene and the disease.
bladder cancer (29 papers, 2011 to 2025). "Northern blot and 5′-RACE analyses revealed that there exist two DEPDC1 transcriptional variants, both of which are overexpressed in bladder cancer cells." (PMID 28969015, 2017). "DEP domain 1 protein (DEPDC1) was initially identified in bladder cancer cells and plays a critical role in the mitotic process." (PMID 40722708, 2025). "DEPDC1, initially identified in bladder cancer, was found to be overexpressed in various cancers including bladder, liver, and lung cancer, and is widely recognized as an oncogene." (PMID 39068164, 2024). "The expression of DEPDC1 is obviously upregulated in some cancers, and the high expression level of DEPDC1 is closely related to the progression of cancer, including hepatocellular carcinoma, bladder cancer, lung adenocarcinoma and gastric cancer." (PMID 36849972, 2023). "Of note, DEPDC1 was found to be highly expressed in bladder cancer, hepatocellular carcinoma, and multiple myeloma, acting as a novel diagnostic marker or prognostic predictor, indicating that overexpression of DEPDC1 might play a role in the development and progression of cancers." (PMID 36309731, 2022). "DEPDC1 is abnormally over-expressed in the prostate, hepatic, breast, and lung cancers, according to recent research, and can predict outcomes in lung and bladder cancer patients." (PMID 36072787, 2022). "Studies have shown that DEPDC1 is significantly elevated in bladder cancer and is important for cancer cell proliferation." (PMID 36072787, 2022). "DEPDC1 was first identified as a novel gene in bladder cancer, wherein it plays an essential role in the growth of bladder cancer cells." (PMID 34268303, 2021). "A DEPDC1-derived short peptide vaccine has demonstrated promising efficacy in preventing bladder cancer recurrence in a phase I/II clinical trial." (PMID 34268303, 2021). "Its function as an oncogene was discovered in bladder cancer based on its interaction with DEPDC1 oncogene." (PMID 33672287, 2021). "Recently, a DEPDC1-derived short peptide vaccine has demonstrated promising efficacy in preventing bladder cancer recurrence in a phase I/II clinical trial." (PMID 34268303, 2021). "Two DEPDC1 transcriptional variants were found by northern blot and 5′-RACE analysis, and both of them were highly expressed in bladder cancer cells." (PMID 31032225, 2019). "It was reported that DEPDC1 was significantly increased in bladder carcinoma and necessary for the proliferation of cancer cells." (PMID 31032225, 2019). "DEPDC1 is highly expressed in various kinds of cancers, like bladder cancer, hepatocellular carcinoma, lung cancer, and nasopharyngeal carcinoma." (PMID 31032225, 2019). "Previous studies showed that DEPDC1 inhibited the transcription of A20 through NF-κB pathway in bladder cancer, hepatic carcinoma, lung cancer, and nasopharyngeal carcinoma, which acted a key role in cell proliferation, tumorigenesis and metastasis." (PMID 31032225, 2019). "We and others have demonstrated that DEPDC1 acts as a transcription repressor to inhibit the transcription of A20, a negative regulator of the NF-κB signaling pathway in bladder cancer cells and HeLa cells." (PMID 28969015, 2017). "To date, only one protein, ZNF224, has been identified to form a complex with DEPDC1 in bladder cancer cells." (PMID 28969015, 2017). "Currently, functional analysis on the implication of DEPDC1 in cancer development has been conducted in bladder cancer, multiple myoloma and prostate cancer." (PMID 28969015, 2017). "DEPDC1 was firstly reported to be aberrantly overexpressed in bladder cancer and has an important role in the bladder cancer development." (PMID 28969015, 2017). "Knockdown of DEPDC1 or inhibition using a specific peptide results in decreased cell proliferation and apoptosis in bladder cancer cell lines." (PMID 26445238, 2015).
bladder cancer (continued). "DEP domain containing 1 (DEPDC1) is a novel TAA classified as cancer-testis antigen that is significantly overexpressed in a majority of bladder cancer specimens." (PMID 24386437, 2013). "DEPDC1 also play an essential role in the growth of bladder cancer cells." (PMID 40018408, 2025). "DEPDC1 was first discovered at an abnormally raised expression in bladder cancer." (PMID 36072787, 2022). "The most common cancer type in which DEPDC1 was shown to play a function was bladder cancer." (PMID 36072787, 2022). "DEPDC1 was firstly reported in bladder cancer with aberrantly high expression; it acted as a transcriptional repressor by forming a complex with zinc finger protein 224 (ZNF224) to suppress A20 transcription, leading to the activation of anti-apoptotic pathway through activating NF-κB pathway." (PMID 31032225, 2019). "The role of DEPDC1 in cancers was mainly found in bladder cancer." (PMID 31032225, 2019). "Notably, a recently developed cell-permeable peptide against DEPDC1 achieved good therapeutic effects in bladder cancer." (PMID 28969015, 2017). "Consequently, knockdown of DEPDC1 inhibited growth and induced apoptosis in bladder cancer, myeloma, and prostate cancer cells." (PMID 28969015, 2017). "Finally, an HLA-DR4 binding DEPDC1191-213 peptide from a new TAA DEPDC1 overexpressed in bladder cancer induced strong Th-cell responses both in Tgm and in PBMCs from an HLA-DR4-positive donor." (PMID 24386437, 2013). "DEPDC1 might play an essential role in the growth of bladder cancer cells." (PMID 25887408, 2015). "For example, CTL induction against DEPDC1 and MPHOSPH1 has been previously observed in patients with bladder cancer in response to a cancer vaccine comprising two peptides administered weekly for 12 weeks." (PMID 38993370, 2022). "High expression of DEPDC1 and MPHOSPH1 was detected by immunohistochemical analysis in around 90% of participants with bladder cancer, similar to previous studies." (PMID 38993370, 2022). "This immunotherapy was restricted to HLA-A*24:02-individuals (more common in Japan) using peptides derived from five cancer-testis antigens (DEPDC1, MPHOSPH1, URLC10, CDCA1, and KOC1) commonly present in bladder cancer." (PMID 38993370, 2022). "Influence of the BC on cell cycle was also noticed, while some proteins like DEPDC1 (DEP domain containing 1) and MPHOSPH1 (M-phase phosphoprotein 1) are usually overexpressed in bladder cancer cells." (PMID 32392774, 2020). "DEP domain containing 1 (DEPDC1) is a newly identified cancer-related and cell cycle related gene and has been demonstrated as a novel therapeutic target for bladder cancer." (PMID 28969015, 2017). "Previous reports showed that DEPDC1 interacts with ZNF224 to repress the transcription of A20, resulting in the activation of the NF-κB pathway in bladder cancer." (PMID 28969015, 2017). "We also found the bona fide driver of melanoma metastasis and invasion NEDD9 as well as DEPDC1 and CDCA3, genes involved in progression of bladder cancer or enhanced proliferation." (PMID 24799129, 2014). "The ZNF224/DEPDC1 complex acted synergistically to enhance cell proliferation, whereas the chemical disruption of this interaction (with 11R-DEP:611-628 peptide) induced apoptosis and suppressed the growth of the bladder cancer cells in vivo and in vitro." (PMID 33672287, 2021). "A peptide derived from DEPDC1 611‐628 amino acid residues (named as 11R‐DEP:611‐628) can disrupt DEPDC1/ZNF224 complex and thus may inhibit cell proliferation of bladder cancer." (PMID 33021072, 2020). "Moreover, DEPDC1 repressed the transcription of A20 through interacting with ZNF224, leading to activate NF-κB pathway in bladder cancer." (PMID 31032225, 2019). "DEPDC1 is over-expressed in various cancers, especially in bladder cancer and a clinical trial using DEPDC1-derived short CTL epitope peptide-vaccination was performed for 6 patients with advanced bladder cancer, although the clinical response was marginal." (PMID 24386437, 2013).
bladder cancer (continued). "The DEP domain 1 protein (DEPDC1) is an oncoprotein containing a DEP domain, which has not been detected in 24 normal human tissues, including normal lung tissue, except testicular surface and was first reported in bladder cancer." (PMID 36849972, 2023).
hepatocellular carcinoma (21 papers, 2016 to 2025). A malignant tumor that arises from hepatocytes. "In addition, several studies have found that longer survival in patients with multiple myeloma and hepatocellular carcinoma was significantly correlated with a lower DEPDC1 expression, suggesting that DEPDC1 may be a new diagnostic marker." (PMID 36072787, 2022). "Research has demonstrated that DEPDC1 is highly expressed in a majority of tumors, including human osteosarcoma, hepatocellular carcinoma, nephroblastoma, anaplastic thyroid carcinoma, colorectal cancer, and oral squamous cell carcinoma." (PMID 40600015, 2025). "Artemisia was essential oil significantly suppressed DEPDC1 expression in hepatocellular carcinoma, which leading to the downregulation of Wnt/β-catenin signaling and epithelial-mesenchymal transition." (PMID 40600015, 2025). "In hepatocellular carcinoma, DEPDC1 had been validated as a contributor to the reconstruction of the tumor microenvironment, serving as a metabolic gene associated with glycolysis." (PMID 40600015, 2025). "DEPDC1 shows up up-regulation within multiple cancer, like gastric cancer, hepatocellular carcinoma, triple-negative breast cancer, prostate cancer and NSCLC." (PMID 38564630, 2024). "Overwhelming evidence indicated the high expression of DEPDC1 in hepatocellular carcinoma samples relative to corresponding adjacent samples, which accelerates tumor cell growth but inhibits their apoptosis." (PMID 38564630, 2024). "It has been reported that, DEPDC1 is a key gene in the transformation of hepatitis B into hepatocellular carcinoma." (PMID 38564630, 2024). "DEPDC1 interference suppressed hepatocellular carcinoma cell proliferation, colony formation and invasion in vitro and HUVEC angiogenesis." (PMID 36849972, 2023). "In hepatocellular carcinoma, DEPDC1, as a metabolic gene related to glycolysis, has been validated as a contributor to the reconstruction of the tumor microenvironment." (PMID 36768316, 2023). "Another previous study reports that DEPDC1 promotes angiogenesis and invasion by activating chemokines in hepatocellular carcinoma." (PMID 34855841, 2021). "Overexpression of DEPDC1 and its oncogenic roles were frequently demonstrated in several tumors, such as hepatocellular carcinoma and prostate cancer." (PMID 32396871, 2020). "DEPDC1 exhibits overexpression in various malignant tumors, including oral squamous cell carcinoma, human osteosarcoma, nephroblastoma, anaplastic thyroid carcinoma, non-small cell lung cancer, hepatocellular carcinoma, and colorectal cancer." (PMID 40600015, 2025). "As only a glycolytic-related gene, DEPDC1 can regulate the malignant progression of oral squamous cell carcinoma through the WNT/β-Catenin pathway, and as one of the prognostic risk predictors of hepatocellular carcinoma." (PMID 39068164, 2024). "DEPDC1, a glycolysis-related gene, has been shown to promote the progression of oral squamous cell carcinoma (OSCC), predict the progression and prognosis of RCC, and serve as a predictor of prognostic risk in hepatocellular carcinoma (HCC)." (PMID 39068164, 2024). "In addition, high DEPDC1 expression mediated by LincRNA regulator of reprogramming (Linc-ROR) accelerated the development of hepatocellular carcinoma and angiogenesis." (PMID 36768316, 2023). "Importantly, increased DEPDC1 has been found to suppress the sensitivity to chemotherapy in hepatocellular carcinoma." (PMID 35582195, 2022). "Additionally, several studies revealed that the higher expression of DEPDC1 was significantly correlated with poorer survival of patients in hepatocellular carcinoma and multiple myeloma, indicating that DEPDC1 might be a new diagnostic marker." (PMID 31032225, 2019). "Yuan16 discovered the high DEPDC1 expression in hepatocellular carcinoma (HCC) tissues at the mRNA and protein levels." (PMID 28000796, 2016).
hepatocellular carcinoma (continued). "In a study with hepatocellular cancer (HCC) cell lines and xenografts, linc-ROR acted as a ceRNA for miR-130a-3p to stabilize DEP domain containing 1 (DEPDC1) mRNA, facilitating progression and angiogenesis." (PMID 36827545, 2023).
prostate carcinoma (10 papers, 2017 to 2024). A carcinoma that arises from epithelial cells of the prostate gland. "The network also created an additional cluster for this region which, through factor analysis, we found is related to the spatial expression of DEPDC1, which was found to be linked to tumor growth and cell proliferation in prostate cancer." (PMID 34638322, 2021). "Ramalho-Carvalho and colleagues reported that miR-130a represses the expression of DEPDC1, and epigenetic disruption of miR-130a causes up-regulation of DEPDC1 in prostate cancer." (PMID 28969015, 2017). "In prostate cancer, DEPDC1 facilitated cell proliferation and tumor growth via activating E2Fsignaling pathway." (PMID 31032225, 2019). "In addition, DEPDC1 could interact with E2F1 and promote its transcriptional activity in prostate cancer, resulting in the activation of the E2F signaling pathway to regulate the G1/S phase cell cycle transition and then increase cell proliferation." (PMID 36768316, 2023).
glioma (8 papers, 2015 to 2024). A benign or malignant brain and spinal cord tumor that arises from glial cells (astrocytes, oligodendrocytes, ependymal cells). "A trial using a polypeptide vaccine targeting LY6K, DEPDC1, KIF20A, and FOXM1 in patients with high-grade glioma showed that the vaccine was well tolerated, elicited an effective immune response, and prevented disease progression for at least 6 months." (PMID 39727968, 2024).
multiple myeloma (8 papers, 2013 to 2022). "In myeloma, DEPDC1 expression has been associated with poor prognosis." (PMID 26445238, 2015). "Importantly, Pttg1 knockdown in myeloma cells leads to a 40 % reduction in DEPDC1 expression." (PMID 26445238, 2015).
nasopharyngeal carcinoma (8 papers, 2017 to 2023). A carcinoma arising from the nasopharyngeal epithelium. "Another study revealed that knocking down DEPDC1 caused a delay in nasopharyngeal cancer cell cycle progression, proliferation, and substantial migratory inhibition." (PMID 36072787, 2022). "In nasopharyngeal carcinomas, suppressing DEPDC1 slows the cell cycle and significantly reduces invasion, migration, and proliferation." (PMID 36072787, 2022). "In nasopharyngeal carcinoma, silence of DEPDC1 resulted in significant reduction of proliferation, migration, invasion, and delay in cell cycle progression." (PMID 31032225, 2019). "Notably, one study also demonstrated that knockdown DEPDC1 resulted in significant inhibition of migration, proliferation and delay in cell cycle progression in nasopharyngeal cancer cells." (PMID 31032225, 2019). "DEPDC1 was reported to be overexpressed at both mRNA and protein levels in nasopharyngeal carcinoma tissues compared with normal or non-tumor tissues, and the siRNA-mediated deletion of DEPDC1 significantly inhibited the proliferation of nasopharyngeal carcinoma cell lines CNE-1 and HNE-1." (PMID 36849972, 2023). "However, the functional involvement and therapeutic potential of DEPDC1 in nasopharyngeal carcinoma (NPC) remains unclear." (PMID 28969015, 2017). "To compare the expression of DEPDC1 in NPC tissues and normal nasopharyngeal tissues, we performed RT-PCR on 51 tissues with biopsy, including 33 patients with nasopharyngeal carcinoma and 18 healthy controls." (PMID 28969015, 2017). "In nasopharyngeal carcinoma, DEPDC1 knockdown downregulated various downstream targets, such as c−Myc, BCL2, MMP2 and MMP9, which participated in proliferation, tumorigenesis, and metastasis, suggesting that DEPDC1 might be a vital factor in these biological processes." (PMID 36768316, 2023).
gastric cancer (7 papers, 2018 to 2024). A primary or metastatic malignant neoplasm involving the stomach. "In addition, up-regulation of DEPDC1 in gastric cancer tissues has been associated with the advanced tumor differentiation and lymph node metastasis." (PMID 38564630, 2024). "For instance, DEPDC1 promoted cancer metastasis and differentiation via accelerating the cell cycle from G1 to S phase in gastric cancer." (PMID 36768316, 2023). "In addition, HPA indicated low levels of DEPDC1 protein in normal stomach tissues and moderate expression level in gastric cancer tissues; however, the expression levels of MET are the opposite." (PMID 34386426, 2021). "Similarly, OS was not significantly different in patients with advanced gastric cancer treated with multiple peptides (DEPDC1, URLC10, FoxM1, Kif20A, and VEGFR1) who were A24(+) compared with A24(–)." (PMID 38993370, 2022).
lung carcinoma (7 papers, 2015 to 2024). "Our previous study revealed that DEPDC1 is expressed in multiple lung cancer cell lines and 11R‐DEP:611‐628 can induce apoptosis of LUAD A549 cells, indicating DEPDC1 plays its role by forming complex with ZNF224 in A549 cells." (PMID 33021072, 2020). "On the contrary, the DEPDC1 levels were depressed in lung cancer cells after their KTN1-AS1 was silenced." (PMID 32396871, 2020). "Afterwards, the genes positively correlated with DEPDC1 in lung cancer were obtained by using UALCAN program analysis, and GO and KEGG analysis revealed that DEPDC1 positively correlated genes were relevant with cell cycle." (PMID 32396871, 2020).
oral squamous cell carcinoma (7 papers, 2022 to 2025). "Oral squamous cell carcinoma (OSCC) is a prevalent malignancy, and a recent study observed that DEPDC1 protein was overexpressed in OSCC tissue with a demonstrated correlation between smoking status and upregulated DEPDC1 expressions." (PMID 36479633, 2023).
colorectal cancer (6 papers, 2021 to 2025). A primary or metastatic malignant neoplasm that affects the colon or rectum. "Recent studies suggested that DEPDC1 protein expression was correlated with poorer TNM stage and recurrence in colorectal cancer." (PMID 40600015, 2025). "Research indicates that SIRT1 can bind to the miR-20b-3p promoter, mediating the miR-20b-3p/DEPDC1 axis and enhancing L-OHP resistance in colorectal cancer." (PMID 39409719, 2024).
triple-negative breast carcinoma (6 papers, 2019 to 2024). An invasive breast carcinoma which is negative for expression of estrogen receptor (ER), progesterone receptor (PR), and human epidermal growth factor receptor 2 (HER2). "For example, over-expressed DEPDC1 is negatively regulated by miR-26b, which facilitates cell proliferation in triple negative breast cancer (TNBC)." (PMID 33287763, 2020). "miR-26b prevents the tumorigenesis of triple-negative breast cancer (TNBC) cells by targeting DEP domain containing 1(DEPDC1) and downregulating FOXM1 expression." (PMID 32714393, 2020). "Since RAS can stimulates FOXM1 expression, our findings also might be used to explain how FOXM1 is up‐regulated by DEPDC1 in triple negative breast cancer cells, which was observed in another study." (PMID 33021072, 2020). "DEPDC1 was shown to be negatively regulated by miR-26b and promoted cell proliferation and tumor growth by upregulating FOXM1 expression in triple-negative breast cancer." (PMID 32149111, 2020).